SLC6A17 (solute carrier family 6 member 17)
Description:
Synaptic vesicle transporter with apparent selectivity for neutral amino acids. The transport is sodium-coupled but chloride-independent, likely driven by the proton electrochemical gradient generated by vacuolar H(+)-ATPase in an overall electrogenic mechanism. May contribute to the synaptic uptake of neurotransmitter precursors in a process coupled in part to vesicle exocytosis.
Synonyms: NTT4; MRT48
Tractability: Small molecule: it belongs to a druggable protein family. Antibody: UniProt predicts a signal peptide or a membrane-spanning region; its Gene Ontology location is reachable by antibodies, with medium confidence. PROTAC: ubiquitination databases record sites on it; its protein half-life has been measured.
Gene: Protein-coding gene on chromosome 1 (110,150,494 to 110,202,202, forward strand). Ensembl gene ENSG00000197106.
Subcellular location: Cytoplasmic vesicle, secretory vesicle, synaptic vesicle membrane; Postsynapse; Presynapse
Subcellular location (Human Protein Atlas): Mitochondria
Gene Ontology:
Molecular function: protein binding; alanine:sodium symporter activity; glycine:sodium symporter activity; proline:sodium symporter activity; transmembrane transporter activity
Biological process: alanine transport; brain development; glycine transport; L-leucine transport; neutral amino acid transport; proline transport; sodium ion transmembrane transport; transport across blood-brain barrier; carboxylic acid transmembrane transport; protein catabolic process
Cellular component: membrane; postsynapse; presynapse; synaptic vesicle; GABA-ergic synapse; glutamatergic synapse; plasma membrane; synapse; synaptic vesicle membrane
Genetic constraint (gnomAD): Loss-of-function variants: 20 observed, 64.38 expected, observed/expected ratio (o/e) 0.31, 90% interval 0.22 to 0.45. The upper end of that interval is the gene's LOEUF score, 0.45, which puts it in group 2 of 6, group 1 being the genes least tolerant of losing a copy. Missense variants: 628 observed, 929.72 expected, observed/expected ratio (o/e) 0.68, 90% interval 0.63 to 0.72. Synonymous variants: 343 observed, 384.64 expected, observed/expected ratio (o/e) 0.89, 90% interval 0.82 to 0.98.
Gene-disease validity (ClinGen):
ClinGen rates the evidence that SLC6A17 causes each of these diseases.
progressive essential tremor-speech impairment-facial dysmorphism-intellectual disability-abnormal behavior syndrome (autosomal recessive): Moderate.
Homologues: Orthologues: chimpanzee SLC6A17 (99% identical), macaque SLC6A17 (99% identical), guinea pig SLC6A17 (97% identical), rat Slc6a17 (97% identical), pig SLC6A17 (97% identical), mouse Slc6a17 (97% identical), dog SLC6A17 (96% identical), rabbit SLC6A17 (90% identical), tropical clawed frog slc6a17 (81% identical), zebrafish slc6a17 (75% identical). Paralogues in human: SLC6A15 (67% identical), SLC6A19 (36% identical), SLC6A18 (35% identical), SLC6A20 (34% identical), SLC6A16 (32% identical), SLC6A7 (30% identical), SLC6A13 (30% identical), SLC6A5 (30% identical), SLC6A3 (29% identical), SLC6A14 (29% identical), SLC6A9 (29% identical), SLC6A2 (29% identical), and 6 more.
Diseases named in the same sentence as SLC6A17 in open-access papers:
SLC6A17 is named in the same sentence as 5 diseases in open-access papers, as found by Europe PMC text mining. Sharing a sentence is not in itself a finding about the gene and the disease. The quoted sentences say what the papers report.
Intellectual disability (3 papers, 2023 to 2024). "The patient also carried a VUS in the SLC6A17 gene [c.335C>T, p.(Pro112Leu)], which encodes for a sodium-dependent amino acid carrier primarily expressed in the brain, and which is associated with intellectual disability." (PMID 39288270, 2024).
breast carcinoma (1 paper, 2022). "The role of MATN4, SLC6A17, and NEUROG2 genes in breast cancer is currently unknown, but they play a role in other cancers, which may be an inspiration for future breast cancer gene research." (PMID 36553681, 2022).
SLC6A17 also shares sentences with these, for which no sentence is quoted: cancer (2 papers); pheochromocytoma (1); tumor (1).